IL1A (interleukin 1 alpha)
Diseases named in the same sentence as IL1A in open-access papers (continued):
Sharing a sentence is not in itself a finding about the gene and the disease.
asthma (continued). "Both IL-1α and IL-1β, for example, are known to be molecules with a strong proinflammatory role, IL-15 has been reported to be elevated in celiac patients in previous studies, and IL-5 plays an important role in the pathophysiology of asthma." (PMID 23533306, 2013). "Similarly, studies from animal models have demonstrated that IL-1 cytokines such as IL-1α and IL-1β play critical roles in the pathogenesis of asthma, chronic obstructive pulmonary disease, acute lung injury and pulmonary fibrosis." (PMID 23029241, 2012). "A recent study showed that the only biomarkers that could distinguish severe or moderate asthma from mild asthma are neutrophil count and IL-8, out of the eight potential biomarkers (IL-8, neutrophils, eosinophils, IL-1Rα, IL-1α, IL-5, IL-6, and RANTES) investigated in BALF." (PMID 23355837, 2013). "Furthermore, given that non-eosinophilic asthma, which is characterized by neutrophilia, is driven by cytokines seen in PTSD including IL-1α, IL-6 and IL-17, we hypothesized that individuals with asthma and PTSD would have distinct inflammatory markers compared to those without PTSD." (PMID 38349898, 2024). "In the context of asthma, bronchoalveolar lavage fluid (BALF) and sputum from asthmatic individuals sensitized to fungi demonstrate elevated IL-1α levels." (PMID 39457624, 2024). "The levels of TNF-α, TNFR2, and CCL-9 in the asthma model group increase, while the levels of IFN-γ, IL-1α, ICAM-1, and IL-4 increased in the Majie cataplasm group, especially IFN-γ and IL-1α." (PMID 35600943, 2022). "On the other hand, in non-T2 asthma models, after epithelial injury, IL-6, TNF, and IL-1a production are stimulated, and neutrophilic inflammation is induced." (PMID 36326393, 2022). "In the asthma model, OVA together with TLR ligands (LPS/flagellin) or house dust extract (HDE) as adjuvants induced a similar accumulation of TNF, IL-1a, IL-1b, and GM-CSF in BALF pointing to the possible role of LPS in the effect with HDE." (PMID 35387007, 2021). "Consequently, airway epithelium in patients with T2 asthma overproduces a broad pallet of pro-inflammatory cytokines and mediators including alarmins (IL-25, IL-33, TSLP), as well as IL-6, IL-8, IL-1α/β, RANTES, or TNF in response to environmental triggers." (PMID 37199256, 2023). "From the result, we can easily see that in the asthma model, the lower content of IL-1α is favorable for Th2 polarization, while Majie cataplasm affects NKs to reverse the shift with the increasing content of IFN-γ and IL-1α." (PMID 35600943, 2022). "IL-1α, another DAMP, is also thought to play a role in asthma and COPD." (PMID 34248677, 2021). "In fact, both cytokines, IL-1β and IL-1α, reduced in our study by brine solution, were displayed to play a significant role in AHR and inflammatory cells influx; their blockade reduced the phenotype of murine asthma." (PMID 32645931, 2020). "Importance of both IL-1 cytokines, IL-1β and IL-1α, in AHR and recruitment of inflammatory cells to the lung was evidenced after blockade with neutralizing antibodies, resulting in attenuated phenotype of murine model of asthma." (PMID 31779093, 2019). "In addition to collagen Iα1, IL-1α/β, but not IL-33, also suppressed the expression of the ECM proteins, periostin and fibronectin, which are known to be altered in expression in asthma." (PMID 32457454, 2020). "Mice lacking IL-1R failed to mount a Th2 immune response and did not develop asthma to HDM, IL-1α acted in an autocrine manner to trigger the release of DC-attracting chemokines, IL-33, and allergic sensitization to HDM was abolished in vivo when IL-1α was neutralized." (PMID 27046957, 2016). "Further, we demonstrate that IL-1α alone was elevated in asthmatic compared to non-asthmatic PAEC-ALI cultures during differentiation, compared to other IL-1 family members and key epithelial mediators shown previously to play a role in asthma (IL-8, GM-CSF, TSLP, and TGF-β1)." (PMID 32457454, 2020).
pancreatic cancer (35 papers, 2005 to 2025). "A recent study identified IL-1α and IL-1β released by pancreatic cancer cells and tumor-associated macrophages as relevant stimuli for TSLP release from CAFs." (PMID 40873585, 2025). "The age-associated decline of DNMT3A enhances IL-1α production, and disrupting IL-1R1 signaling early during tumor development normalized myelopoiesis and slowed the growth of lung, colonic, and pancreatic tumors." (PMID 39236155, 2024). "Cancer-cell-derived IL-1α has previously been shown to induce a tumor-promoting immune microenvironment by activating the cancer-associated fibroblasts in pancreatic cancers." (PMID 37835389, 2023). "IL-1α has been shown to promote proliferation, adhesion, and migration of pancreatic cancer cell lines, and is associated with the activation of Ras and the downstream ERK signaling pathway." (PMID 26135631, 2015). "Stimulation with recombinant human IL-1α (rIL-1α) of pancreatic cancer cells on Coll IV furthermore enhanced the association of FAK with β1 integrin." (PMID 16209712, 2005). "We found that TGFβ down-regulated the expression of IL-1R1 on the stellate cells, which resulted in inhibition of the responses to IL-1α, with loss of the stimulatory effect of IL-1α on the ability of pancreatic stellate cells to enhance migration of the pancreatic carcinoma cells." (PMID 27473228, 2016). "The secretion of IL-1α by the cancer cells enhances the metastatic potential, immune evasion capabilities, and proliferation rate in pancreatic cancer." (PMID 38544822, 2024). "When exposed to hypoxic conditions, these fibroblasts undergo activation into an inflammatory state, triggered by interleukin-1α (IL-1α) released by pancreatic cancer cells." (PMID 38544822, 2024). "The frequency of RAS mutations in pancreatic carcinoma is high; therefore, although many SASP were found in PAAD, we chose IL-1α and IL-6 for further analysis." (PMID 36622275, 2023). "IL-1α activates inflammatory CAFs in pancreatic cancer through the JAK-STAT pathway and is antagonized by TGF-β." (PMID 35493517, 2022). "The IL-1 pathway significantly promoted pancreatic tumor progression and immune cell infiltration by controlling the secretion of IL-1α and other SASP factors." (PMID 34366891, 2021). "Meanwhile, IL-1α can enhance the metastatic potential of pancreatic tumor cells by maintaining the constitutive activation of nuclear factor κ-B (NFκB), promoting the secretion of hepatocyte growth factor (HGF), and can facilitate angiogenesis." (PMID 34187428, 2021). "We show in vitro that IL-1α and IL-1β released by pancreatic cancer cells and tumor cell-conditioned macrophages are crucial for TSLP secretion by CAFs." (PMID 30760333, 2019). "Pancreatic cancer cell-derived IL-1α was similarly shown to promote hepatocyte growth factor secretion by fibroblasts, promoting pancreatic cancer invasion, proliferation and angiogenesis." (PMID 31231372, 2019). "It has also been shown that HGF-secretion from fibroblasts is increased by IL-1α or by co-culture with IL-1α-expressing pancreatic cancer cells." (PMID 29069737, 2017). "We previously demonstrated that IL-1α increases the ability of pancreatic stellate cells to enhance migration of pancreatic cancer cells." (PMID 29069737, 2017). "Tumor stroma interactions induced by IL-1α/IL-1R1 signaling have been shown to be involved in pancreatic cancer cell migration." (PMID 27473228, 2016). "It has also been shown in pancreatic cancer cells that IL-1α exerts strong stimulatory effects on PSCs by inducing and sustaining a constitutive NFkB activation, associated with a metastatic phenotype." (PMID 27473228, 2016). "In the MIA PaCa2 pancreatic cancer cell line, IL-1β reduced adhesion to laminin while IL-1α increased fibronectin adhesion but impaired collagen I adhesion." (PMID 27556857, 2016).
pancreatic cancer (continued). "We have previously reported that IL-1α produced by pancreatic cancer cells can activate and sustain the expression of inflammatory factors produced by PSCs and promote cancer cell migration." (PMID 27473228, 2016). "In pancreatic carcinoma, IL-1α was found to sustain the expression of inflammatory factors in the microenvironment and enhance the migratory capacity of the cancer cells." (PMID 27473228, 2016). "In the present work we have studied effects of IL-1α and TGFβ in stromal cell-induced migration of pancreatic carcinoma cells." (PMID 27473228, 2016). "We herein demonstrated that the proliferation of pancreatic cancer cells was enhanced by exposing to IL-1α." (PMID 16504015, 2006). "In this study, we demonstrate that IL-1α-induced proliferation, adhesion and migration of pancreatic cancer cells correlated with activation of Ras and downstream ERK pathway." (PMID 16504015, 2006). "Inhibitory antibodies against α6 and β1 integrin inhibited the baseline and IL-1α-induced proliferation of all three pancreatic cancer cell lines." (PMID 16504015, 2006). "IL-1α also enhanced the adhesion and migration of pancreatic cancer cell lines expressing the IL-1RI, and these enhancements correlated with the enhancement of α6β1-integrin and uPA/uPAR expression." (PMID 16504015, 2006). "Our results suggest that IL-1α induces discernibly aggressive capability in pancreatic cancer and that these regulations can be helpful to understand biological processes for better translational treatment for pancreatic cancer patients." (PMID 16504015, 2006). "All three pancreatic cancer cell lines showed significant enhancement of migration in the presence of IL-1α." (PMID 16504015, 2006). "IL-1α-induced migration of pancreatic cancer cells was inhibited by anti-α6 integrin, anti-β1 integrin, and anti-uPAR antibodies." (PMID 16504015, 2006). "IL-1α enhanced the proliferation, adhesion, and migration in pancreatic cancer cells, and IL-1α-induced alterations of uPA/uPAR expression correlated with the increased the migration of pancreatic cancer cells." (PMID 16504015, 2006). "In this study, we have determined the enhancement of α6β1-integrin expression by IL-1α and the subsequent increased migration of pancreatic cancer cell lines which express IL-1RI protein to Matrigel, which contains several ECM proteins." (PMID 16504015, 2006). "Based on these results, IL-1α induces discernibly aggressive capability in pancreatic cancer and these regulations can be helpful to understand biological processes of pancreatic cancer." (PMID 16504015, 2006). "In this study, the similarity in the time course over which FAK and ERK1/2 were activated in response to IL-1α and adhesion to Coll IV of pancreatic cancer cells were observed." (PMID 16209712, 2005). "PD98059, a MEK inhibitor, also inhibited IL-1α-induced enhancement of adhesion and invasion in pancreatic cancer cells." (PMID 16209712, 2005). "FAK phosphorylation was observed by adhesion to Coll IV, furthermore, stronger FAK phosphorylation was observed by stimulation with IL-1α of pancreatic cancer cells adhered to Coll IV in time-dependent manner." (PMID 16209712, 2005). "The inhibitory antibodies against β1 integrin subunit treatment similarly inhibited the IL-1α-induced enhancement of adhesion and invasion in all three pancreatic cancer cells." (PMID 16209712, 2005). "Genistein and PD98059 (a MEK inhibitor) also inhibited these enhancements of adhesion and invasion by IL-1α stimulation in pancreatic cancer cells." (PMID 16209712, 2005). "IL-1α and IL-1β from pancreatic cancer cells released TSLP from CAFs." (PMID 40873585, 2025). "The inflammatory cytokines TNF and IL-1α are also known to promote pancreatic cancer." (PMID 37814340, 2023). "IL1A/IL-1R1 signaling was involved in pancreatic cancer cell migration." (PMID 36741321, 2023). "These authors demonstrated that genetic ablation of IL-1α decreases pancreatic cancer progression." (PMID 36982207, 2023).
pancreatic cancer (continued). "Similarly, S100 proteins and IL-1α appear to have important roles in promoting pancreatic tumor progression." (PMID 34187428, 2021). "Accordingly, IL-1α deletion delayed cancer progression in a mouse model of pancreatic cancer; in this model, a decrease in the number and grade of PanIN (Pancreatic Intraepithelial Neoplasia) lesions was observed in IL-1α-null mice compared to their WT counterparts." (PMID 34621683, 2021). "Indeed, bioinformatics analyses of the TCGA database revealed a positive correlation between CD137 and IL1A gene expression in 166 human pancreatic cancer tissues (r = 0.274, P < 0.001)." (PMID 31288851, 2019). "For instance, the expression of CD137 in SW1990 pancreatic cancer cells seems to be mainly regulated by the IL-1α through the NF-κB pathway, since the neutralizing IL-1α antibody could profoundly decrease the expression of CD137." (PMID 31288851, 2019). "Furthermore, we also found that the NF-κB pathway was mainly stimulated by the K-Ras-induced secretion of interleukin-1α (IL-1α) which promoted the transcription of the CD137 gene in pancreatic cancer cell lines." (PMID 31288851, 2019). "TGFβ inhibits IL-1α-mediated PSC stimulation of pancreatic cancer cell migration." (PMID 29069737, 2017). "SMAD7 might be a target for inhibition of IL-1α-dependent stimulation of pancreatic cancer cell migration." (PMID 27473228, 2016). "While their association with HGF has not been fully elucidated in pancreatic cancer, what is understood is that the expression of IL-1α by pancreatic cancer cell lines promotes HGF production in stromal cells to facilitate tumor-promoting properties." (PMID 26404380, 2015). "Based on these findings, we conclude that IL-1α can induce selective upregulation of α6β1-integrin and uPA/uPAR in pancreatic cancer cells and these changes may modulate the aggressive functions of pancreatic cancer." (PMID 16504015, 2006). "IL-1α also induced enhancement in the expression of uPA/uPAR in pancreatic cancer cells." (PMID 16504015, 2006). "In this study, we investigated whether interleukin (IL)-1α induces the alterations of integrin subunits and urokinase plasminogen activator/urokinase plasminogen activator receptor (uPA/uPAR) expression in pancreatic cancer cells." (PMID 16504015, 2006). "In this study, we have focused in identifying some of the molecules that are regulated by IL-1α with a view to gain better understanding of the IL-1α induced molecular mechanisms that may contribute to the progression and dissemination of pancreatic cancer." (PMID 16504015, 2006). "Furthermore, stronger FAK phosphorylation was observed by stimulation with IL-1α of pancreatic cancer cells adhered to Coll IV." (PMID 16209712, 2005). "Furthermore, we demonstrated that a MEK inhibitor PD98059 inhibited IL-1α-induced enhancement of adhesion and invasion in pancreatic cancer cells." (PMID 16209712, 2005). "Moreover, cancer cell derived of IL-1α can promote the angiogenesis of pancreatic cancer cell lines with high metastasis to the liver, and actively regulate angiogenesis through the effect on interstitial cells of colon cancer, thus promoting the metastasis of distant organs, such as liver." (PMID 34930323, 2021). "In addition, since TGFβ has an inhibitory role in the regulation of IL-1α-mediated cross-talk between pancreatic cancer cells and PSCs we also examined how IL-1α and TGFβ can modulate the level of HGF expressed by the PSCs and how this affects cancer cell DNA synthesis and migration." (PMID 29069737, 2017). "To determine whether IL-1α have any effect on the adhesion of pancreatic cancer cells, we investigated the adhesive response of pancreatic cancer cell lines to laminin, the putative ligand of the α6β1-integrin, in response to rIL-1α in pancreatic cancer cells." (PMID 16504015, 2006).
pancreatic cancer (continued). "The present study has demonstrated that the CD137 protein was expressed on pancreatic cancer cell surface, and has identified a novel mechanism by which K-Ras regulates CD137 in pancreatic cancer cells through MAPK and NF-κB pathways stimulated by IL-1α." (PMID 31288851, 2019). "In contrast to in vivo or in vitro DMXAA-treated DCs and macrophages, pancreatic cancer epithelial cells produced little if any TNFα, VEGF or IL-1α." (PMID 31036082, 2019). "Analysis of the TCGA (the cancer genome atlas) database also revealed a significant correlation between IL-1α and CD137 expression (r = 0.274) in tumor samples from pancreatic cancer patients (P < 0.001)." (PMID 31288851, 2019). "Correlation of VEGF production with IL-1α and IL-6 in cell lines suggests that the expression of VEGF is regulated by IL-1α and IL-6 in pancreatic cancer and in adenoma cells." (PMID 31419243, 2019). "Inhibition of α6, β1 integrin, or uPAR signaling pathway inhibited IL-1α-induced activation of Ras/ERK pathway with subsequent inhibition in proliferation, adhesion and migration of pancreatic cancer cells." (PMID 16504015, 2006). "IL-1α enhanced the activation of Ras, as evidenced by the increased Ras-GTP levels in pancreatic cancer cells." (PMID 16504015, 2006). "IL-1α stimulation and Coll IV adhesion enhanced the activation of Ras, as evidenced by the increased Ras-GTP levels in three pancreatic cancer cell lines." (PMID 16209712, 2005). "IL-1α stimulation and Coll IV adhesion enhanced the activation of Ras, as evidenced by the increased Ras-GTP levels in pancreatic cancer cells." (PMID 16209712, 2005). "In line with this, we previously showed that pancreatic tumor organoids from cachectic and non-cachectic pancreatic cancer patients expressed variable levels of known cachexia-associated cytokines, including IL-6, TNF-α, IL-8, IL-1α, IL-1β, Mcp-1, and LIF." (PMID 38339292, 2024). "Moreover, several critical inflammatory cytokines including TNFα, IFN-γ, IL-1α, and IL-6 were markedly increased within DMXAA-treated pancreatic tumors compared to control tumors." (PMID 31036082, 2019). "Our findings indicate that tumor released IL-1α and IL-1β and ASC are key regulators of TSLP secretion by CAFs and their targeting should ultimately dampen Th2 inflammation and improve overall survival in pancreatic cancer." (PMID 30760333, 2019). "Stable overexpression of IL-1α in the normally non-metastatic IL-1α negative pancreatic carcinoma cell line MIaPaCa-2 enhanced NF-κB production and cellular invasion in vitro, and resulted in liver metastasis following orthotopic injection in murine models." (PMID 31231372, 2019). "IL-1α-induced activation of Ras and downstream ERK pathway can be inhibited by using inhibitory antibodies against α6 and β1 integrin and uPAR, consistent with the inhibition of proliferation, adhesion and migration of pancreatic cancer cells." (PMID 16504015, 2006). "We also proved that IL-1α had no demonstrable effect on pancreatic cancer cell lines without expressing IL-1RI." (PMID 16504015, 2006). "To estimate whether IL-1α can activate Ras/ERK pathway to regulate proliferation, adhesion and migration of pancreatic cancer cells, we investigated the effect of IL-1α on this pathway." (PMID 16504015, 2006). "IL-1α-induced activation of Ras and downstream ERK can be inhibited by using inhibitory antibodies against α6 and β1 integrin and uPAR, consistent with the inhibition of proliferation, adhesion and migration of pancreatic cancer cells." (PMID 16504015, 2006). "While not statistical affecting the apoptosis of pancreatic cancer cells, IL-1α-induced adhesion and invasion on Coll IV were inhibited with FAK gene silencing by siRNA, β1 integrin blocking, and inhibition of FAK phosphorylation." (PMID 16209712, 2005).